ALB (albumin)
Diseases named in the same sentence as ALB in open-access papers (continued):
Sharing a sentence is not in itself a finding about the gene and the disease.
malnutrition (continued). "In addition, albumin is an important biochemical indicator of nutritional status, and clinicians often use albumin levels to assess a patient’s risk of malnutrition." (PMID 41584588, 2025). "This may be associated with the overall higher comorbidity burden in the dependent patients (for example, a greater prevalence of underweight status in the dependent group may be associated with lower albumin values due to malnutrition)." (PMID 40230736, 2025). "A low albumin concentration was reported to be associated with slower gait speed and malnutrition, indicating that it may impair the effects of resistance training." (PMID 41041271, 2025). "Decreased serum albumin levels are associated with the severity of liver cirrhosis, and hypoalbuminemia is a strong predictor of poor prognosis in cirrhosis due to inflammation and malnutrition." (PMID 40281590, 2025). "Low albumin levels may indicate underlying conditions such as malnutrition or liver dysfunction, which can make gastrointestinal blood vessels more fragile and increase the risk of bleeding." (PMID 41551318, 2025). "Our analysis revealed significant negative correlations between VAT SUVmean and nutritional markers (albumin and prealbumin), which may be associated with increased energy expenditure during malnutrition." (PMID 40558306, 2025). "Patients at risk of malnutrition exhibited significantly lower arm circumference (p: 0.000), calf circumference (p: 0.002), lymphocyte counts (p: 0.000), hemoglobin (p: 0.018), albumin (p: 0.001), and BMI (p: 0.038), as well as significantly higher age (p: 0.000) and CRP levels (p: 0.000)." (PMID 40507738, 2025). "While the median albumin levels from the groups of inpatients with at-risk malnutrition and normal nutritional status were similar, the range of values suggested that the number of people with high albumin concentrations was higher in the group with normal nutritional status." (PMID 40094974, 2025). "However, low albumin levels are typically associated with clinical conditions such as malnutrition, severe inflammation, liver disease, or renal dysfunction." (PMID 39857079, 2025). "Low albumin levels may indicate increased catabolism and malnutrition, which is a known risk factor for anaemia." (PMID 39901231, 2025). "Lower albumin levels and hemoglobin levels were linked to higher CI occurrence, suggesting that malnutrition and anemia, common among MHD patients, might contribute to poor cognitive function." (PMID 40660151, 2025). "Serum albumin may notbe a direct causal factor but rather a surrogate marker of underlyingpathophysiological conditions, such as chronic inflammation, malnutrition, orsystemic illness." (PMID 40927110, 2025). "In addition to inflammation, albumin is a powerful integrative biomarker of overall health deterioration across multiple physiological systems, including malnutrition, liver and gastrointestinal disease, and is associated with frailty." (PMID 40275223, 2025). "Therefore, a reduction in albumin levels signifies not only malnutrition, but also increases the risk of GIB due to its impact on plasma osmotic pressure, vascular permeability and inflammation." (PMID 41551318, 2025). "Conversely, albumin functions crucially in maintaining oncotic pressure and exhibits antioxidant properties; reductions in albumin levels (hypoalbuminemia) are linked to inflammation, malnutrition, and adverse cardiovascular outcomes." (PMID 41144534, 2025). "Although albumin, transferrin, and total cholesterol are dependent on several factors, low serum levels together with reduced ingestion, weight loss, and low BMI supported a malnutrition diagnosis at baseline in all of the patients." (PMID 41007653, 2025). "Our interpretations are supported by previous studies that suggested that albumin and hemoglobin associations might be explainable by the presence of the increased nutritional risk and malnutrition." (PMID 40836330, 2025).
malnutrition (continued). "Hypoalbuminaemia: Albumin levels below 30 g/L indicate nutritional deficiency and hinder healing." (PMID 40936636, 2025). "One of the limitations of the current study was the inability to do a biochemical assessment of nutrition and micronutrient status, like serum pre-albumin, which is a more specific biomarker of nutritional deficiency that plays an essential role in the recovery of patients during management." (PMID 40773483, 2025). "The RAR index proposed in this study integrates both RDW and albumin, simultaneously reflecting two critical pathophysiological processes—systemic inflammation and nutritional deficiency—and demonstrates enhanced prognostic capability for survival relative to each parameter individually." (PMID 41561745, 2025). "Reduced albumin and total cholesterol levels are indicative of malnutrition or underlying health conditions, which may compromise the body’s capacity to heal and recuperate following surgical intervention, thereby impacting ambulatory function." (PMID 38376838, 2024). "In our opinion, PWH in patients with spinal tuberculosis due to pulmonary tuberculosis may be caused by malnutrition of serum albumin in patients." (PMID 39671379, 2024). "For example, as patients with preoperative weight loss were significantly more likely to have low albumin levels suggestive of malnutrition, these effects may reflect the impact of malnutrition on outcomes." (PMID 38561849, 2024). "Low serum albumin concentrations may be caused by liver damage during acute inflammation or increased renal excretion, malnutrition, increased catabolism, intestinal loss, severe volume overload, and escape to interstitial spaces." (PMID 38773489, 2024). "Hence, low albumin levels in the blood have been regarded as a proxy indicator of malnutrition risk." (PMID 39599746, 2024). "Although the presence of more extended neoplastic processes is expected to be associated with a higher rate of malnutrition defined by a lower albumin level, a statistically significant correlation was only observed between preoperative levels of CA125, NLR and PLR and lower albumin levels." (PMID 38254745, 2024). "Low levels of albumin often suggest malnutrition, which can increase the risk of infection." (PMID 38222754, 2024). "This could result from pathophysiological changes that malnutrition can cause in malnourished children as a decrease or a delay in absorption, higher body water level, or reduced albumin concentration." (PMID 39544493, 2024). "The MNA scale has proven useful for identifying risk of malnutrition, proving to be even more effective than assessing serum albumin levels alone; furthermore, it has shown predictive value in relation to outcomes such as mortality and emergency room discharge in older adults." (PMID 39203799, 2024). "Our findings indicate that serum albumin may assist perioperative risk assessment, and prompt correction of hypoalbuminemia and malnutrition could reduce short-term readmissions after hip fracture surgery in this high-risk population." (PMID 38528491, 2024). "Firstly, in older adults, malnutrition, either due to intrinsic nutritional deficiency or age-related diseases, may lead to a decrease in albumin levels, which is considered one of the main indicators of nutritional status in patients." (PMID 39114122, 2024). "Albumin participates in manyphysiological processes, such as binding various compounds, maintaining thecolloidal osmotic pressure, and decreasing platelet aggregation.Hypoalbuminemia is usually considered to be caused by malnutrition, inflammation,or cachexia." (PMID 39076545, 2024). "In addition, patients with both sarcopenia and frailty are associated with lower albumin levels, which are attributable not only to cirrhosis but also to malnutrition (p = 0.0060)." (PMID 39795544, 2024).
malnutrition (continued). "The observed association between lower serum albumin and higher MetS risk may be mediated through malnutrition, suggesting nutrition improvement as a potential avenue to mitigate MetS." (PMID 39480760, 2024). "Therefore, albumin more accurately predicts the risk of adverse outcomes in patients, diverging from its traditional associated with malnutrition." (PMID 39618077, 2024). "Moreover, pulmonary infection, NIHSS scores, hemoglobin, prealbumin, serum albumin, and total protein were identified as independent risk factors for malnutrition in these patients." (PMID 38694222, 2024). "This may be related to the reduced renal function and excessive loss of albumin leading to malnutrition in patients with CKD." (PMID 39726875, 2024). "Albumin and prealbumin deficiency may predict the risk of malnutrition associated with inflammation in patients with cancer." (PMID 39619813, 2024). "This could, in part, be associated with decreased intake of Ca with malnutrition or hyporexia, and with hypoalbuminemia secondary to protein malnutrition (a large portion of Ca is albumin-bound)." (PMID 39641092, 2024). "Factors associated with malnutrition were small waist circumference and low albumin levels." (PMID 39683376, 2024). "Potential additional or combined effects of albumin levels and cognitive impairment on the risk of death in older adults, malnutrition, inflammation, and oxidative reactions may be common factors mediating the observed associations in this study." (PMID 39114122, 2024). "Patient-related factors that may cause AL include preoperative malnutrition, preoperative albumin level of ≤3.5 g/dL, ASA score of ≥3, prolonged surgery, emergency surgery, chronic steroid use, higher CCI score, and so on." (PMID 39314555, 2024). "Consequently, low preoperative albumin levels indicate a state of malnutrition, advanced disease status, and increased risk for postoperative complications." (PMID 38707022, 2024). "In addition, low albumin levels are one of the indicators of cancer-associated malnutrition and can be an important indicator of poor prognosis." (PMID 39061152, 2024). "We hypothesize that high risk of malnutrition, indicated by low serum albumin and PNI levels, is prevalent among gynecologic cancer survivors with LLL, and addressing these nutritional challenges could improve their overall prognosis and quality of life." (PMID 39529928, 2024). "Low serum albumin levels in older adult patients may reflect malnutrition and severe inflammation caused by TB infection." (PMID 39882120, 2024). "Notably, obese patients in the weight loss group were more likely to have preoperative albumin levels suggestive of malnutrition, providing further evidence of a potential impact of malnutrition on outcomes." (PMID 38561849, 2024). "Therefore, a decrease in albumin levels indicates malnutrition and a decrease in immune function, which increases the risk of pulmonary infection in elderly bedridden patients." (PMID 39398953, 2024). "Serum albumin deficiency is an identified risk factor for malnutrition in patients undergoing HD." (PMID 38536779, 2024). "Furthermore, lymphocyte count, hemoglobin, albumin, and total cholesterol levels were considerably lower (all P < 0.001) in patients at risk of malnutrition or malnourished, whereas Ln(SII) was much higher (P < 0.001) than in the adequate nutrition group." (PMID 38178005, 2024). "Compared to other indicators such as this, PNI, combined with serum albumin level and lymphocyte count, may be a useful screening tool to identify patients at risk of malnutrition." (PMID 38431559, 2024). "The MNA, together with albumin and vitamin D levels, could be routinely used to detect the risk of malnutrition and apply nutritional intervention strategies that improve health outcomes in older patients with RA." (PMID 37630691, 2023).
malnutrition (continued). "In contrast, subgroup analyses according to patients with low serum albumin indicate that the weak association between the high iron status and patient survival would be associated with the confounding effect of inflammation or malnutrition." (PMID 37299540, 2023). "The decreased levels of ALB caused by UC in the present study may be related to malnutrition induced by chronic inflammatory conditions or reduced albumin synthesis due to poor liver function." (PMID 38298515, 2023). "Besides the association between low serum albumin levels and malnutrition, these findings have additionally been supported by the decline in the function of albumin as an extracellular antioxidant agent." (PMID 37957767, 2023). "A study carried out in patients with intra-capsular fractures, found that albumin was an independent risk factor for long-term mortality (up to 9 years), and related it to previous poor health, in-hospital complications, as well as a marker of malnutrition." (PMID 37688755, 2023). "Membrane permeability is limited by the need to retain essential proteins such as albumin, as albumin loss may lead to the development of malnutrition." (PMID 36829639, 2023). "The low level of albumin caused by malnutrition affects the osmotic pressure in patients with heart failure, causing edema in the gastrointestinal tract and malabsorption, both of which increase malnutrition and reduce the absorption of diuretics." (PMID 37791200, 2023). "A well-known association with low levels of albumin in the systemic circulation is malnutrition, which may correspond to an unfavorable diet that appears to be more common in these patients." (PMID 37367859, 2023). "The major clinical consequence of PEI is maldigestion, resulting in malabsorption, malnutrition, and the ensuing nutritional deficiencies (including albumin, pre-albumin, transferrin, lipoproteins, fat soluble vitamins, calcium, magnesium, zinc, thiamine, and folic acid)." (PMID 37173931, 2023). "In addition, the association between malnutrition defined with serum albumin levels and severe periodontitis were associated significantly (multivariate model, OR: 2.23, 95% CI 1.11–4.46, p = 0.024)." (PMID 37479734, 2023). "Although the serum albumin level has been well investigated and established as a marker of MICS for mortality prediction, the level of serum albumin was shown to be associated with fluid overload as well as malnutrition and inflammation in patients undergoing dialysis." (PMID 36678182, 2023). "Although albumin, transferrin, and total cholesterol are dependent on several factors, low serum levels together with reduced ingestion, weight loss, and low BMI inferred a significant prevalence of malnutrition at baseline (N = 12; 40%)." (PMID 38201958, 2023). "The cause of the decrease in total protein and albumin may be malnutrition leading to low cellular immunity." (PMID 37791165, 2023). "In our study, we observed that patients with low LDL-C levels tended to have low levels of serum albumin and phosphate, which may indicate malnutrition or an inflammatory state associated with an increased risk of mortality." (PMID 37784041, 2023). "The major determinant of albumin production under physiological conditions is energy supply in which malnutrition is associated with reduced serum albumin levels, whereas high serum albumin levels have been observed in overnutrition conditions such as obesity and metabolic syndrome." (PMID 38004051, 2023). "Malnutrition and inflammation both reduce albumin concentration by decreasing its synthesis, and inflammation is associated with a greater fractional catabolic rate and increased transfer of albumin out of the vascular compartment." (PMID 37737253, 2023). "These contradictory findings may be related to the nutritional status and serum albumin levels of patients, as malnutrition and inflammation are both associated with increased all-cause and cardiovascular mortality in patients undergoing HD." (PMID 37791567, 2023).
malnutrition (continued). "Malnutrition in critically ill patients causes severe physiological stress, leading to a change in hormone release and a resulting altered metabolic rate, altered use of energy sources, and decreased albumin production." (PMID 37342623, 2023). "Additionally, malnutrition associated with low serum albumin at admission is independently associated with a greater risk for bleeding events in patients with AMI undergoing PCI." (PMID 37875955, 2023). "Another possible justification could be, in malnutrition associated glucose metabolic alteration leads to insulin resistance, which inhibits serum albumin gene expression." (PMID 36869395, 2023). "However, our results suggest that weight loss in the previous year, underweight BMI classification, and decreased oral function in older adults aged ≥75 years are associated with malnutrition and risk of low albumin levels." (PMID 37947552, 2023). "This low BMI could reflect a state of malnutrition secondary to prolonged dysphagia and inadequate oral intake, which was confirmed by the serum albumin findings, which decreased significantly in association with mucosal perforation." (PMID 37052709, 2023). "Therefore, the serum urea-to-albumin ratio was implemented to determine the severity of the underlying diseases including trauma, cancer, malnutrition, hypovolemia, and systemic inflammation, as well as hepatic and/or renal insufficiency." (PMID 37240644, 2023). "According to various studies malnutrition is directly associated with serum albumin." (PMID 36869395, 2023). "Significant weight loss and lower albumin levels may be associated with disease progression or malnutrition, increasing the risk of complications that may require ED visits." (PMID 38055320, 2023). "Previous studies have already confirmed the association between lower SCr, lower albumin values and a higher N/L ratio at dialysis initiation and higher mortality; this reflects the association between malnutrition, inflammation and cardiovascular disease and mortality." (PMID 36769658, 2023). "In the performed total protein and albumin test analysis, a reduction in total protein concentration was present in 19%, while albumin concentration was reduced in 17% of patients, which necessitated an additional verification of patients for the source of protein loss and malnutrition." (PMID 37762958, 2023). "In cancer patients, hypoalbuminemia may be caused by decreased synthesis, increased consumption, and loss of serum ALB, which is related to inflammation and malnutrition during cancer development and progression." (PMID 38274836, 2023). "Increased risk of major bleeding in patients with low albumin levels may be attributed to vitamin C and K deficiency, specifically in the setting of malnutrition." (PMID 37108536, 2023). "In addition, low albumin, a marker of inflammation and malnutrition, has been shown to increase susceptibility to infection and death in HD patients." (PMID 37512123, 2023). "Since the limitation of nutritional assessment with serum albumin level alone has been pointed out, it might indicate severe malnutrition in the high-risk foot group in older patients." (PMID 35268404, 2022). "Low albumin levels may be associated with malnutrition, asymptomatic liver disease, or other chronic diseases; thus, they are also inevitably associated with mortality." (PMID 36275426, 2022). "Underestimation of BMI in detecting malnutrition might be caused by body fluid imbalance, which includes the presence of ascites or oedema caused by a decrease in albumin." (PMID 35011097, 2022). "Among the biochemical results, in AD population, malnutrition indicators (erythrocyte, hemoglobin, serum albumin, and total protein) were most significantly associated with cognitive function, as was free triiodothyronine (FT3) levels which had been observed in previous study." (PMID 35265656, 2022).